TLR3 (toll like receptor 3)
Diseases named in the same sentence as TLR3 in open-access papers (continued):
Sharing a sentence is not in itself a finding about the gene and the disease.
familial hypertrophic cardiomyopathy (1 paper, 2013). Hypertrophic cardiomyopathy caused by mutations in the genes encoding components of the sarcomere, in the absence of predisposing conditions. "Specifically SLC25A4 is connected with progressive external ophthalmoplegia and familial hypertrophic cardiomyopathy, TLR-3 with susceptibility or resistance to some kinds of infections, F11 with deficiency in coagulation factor XI and CYP4V2 with Bietti crystalline corneoretinal dystrophy." (PMID 24176130, 2013).
familial Mediterranean fever (1 paper, 2025). Familial Mediterranean fever (FMF) is an autoinflammatory disorder characterized by recurrent short episodes of fever and serositis resulting in pain in the abdomen, chest, joints and muscles. "A genetic predisposition to the disease has been suggested, with associations to familial Mediterranean fever (FMF) and mutations in specific genes, such as TLR3 and UNC-93B, which are involved in immune regulation." (PMID 40271303, 2025).
Fulminant hepatitis (1 paper, 2013). Acute hepatitis complicated by acute liver failure with hepatic encephalopathy occurring less than 8 weeks after the onset of jaundice. "Therefore, we aimed to investigate the expression of IL-33 in murine fulminant hepatitis induced by a Toll like receptor (TLR3) viral mimetic, poly(I:C) or by pathogenic mouse hepatitis virus (L2-MHV3)." (PMID 24058536, 2013).
fungal keratitis (1 paper, 2022). "Jeyalatha Mani et.al found that the expression of pro-inflammatory factors (IL-1β, IL-8, and IFN-γ) and TLRs (TLR-3/4/6) were significantly downregulated after CXL treatment in patients with fungal keratitis, suggesting that CXL may exerts an anti-inflammatory effect via TLRs pathway." (PMID 35836944, 2022).
gingivitis (1 paper, 2019). A disorder involving inflammation of the gums; may affect surrounding and supporting structures of the teeth. "TLRS 1, 7, and 9 were only detected after pathogenic biofilm exposure (gingivitis and cariogenic) and TLR3 was weakly expressed after exposure to all three biofilms but not in unexposed RHG." (PMID 31448244, 2019).
glomerular diseases (1 paper, 2013). "Based on our recent experimental studies using cultured normal human mesangial cells (MCs), we found that novel TLR3-mediated signaling pathways in MCs may be involved in the pathogenesis of glomerular diseases." (PMID 23935652, 2013). "However, the precise role of the interaction between TLR3, MDA5, and RIG-I in mesangial inflammation in human glomerular diseases remains to be elucidated." (PMID 23935652, 2013).
glucose metabolic disorders (1 paper, 2020). "Among our patients, we noticed a significant drop in TLR3 expression after a successful DAA treatment, which suggests that they are less prone to developing glucose metabolic disorders, despite increased BMI." (PMID 32587314, 2020).
Griscelli syndrome (1 paper, 2020). Griscelli syndrome (GS) is characterized by silvery gray sheen of the hair and hypopigmentation of the skin which can be associated to neurological impairment (type 1), immunodeficiency (type 2) or be isolated (type 3). "In contrast, TLR3 increases melanosome transport to transfer to keratinocytes through Rab27A, the responsible molecule of Griscelli syndrome." (PMID 33371432, 2020).
hemorrhagic disease (1 paper, 2023). Spontaneous or near spontaneous bleeding caused by a defect in clotting mechanisms (blood coagulation disorders) or another abnormality causing a structural flaw in the blood vessels (hemostatic disorders). "In white-tailed deer, the expression of TLR3 mRNA is reported to be higher in tissues said to be typically involved in hemorrhagic disease." (PMID 36833353, 2023). "One study examined the expression of TLR3 mRNA in various tissues in white-tailed deer, stating that tissues with higher baseline TLR3 expression are from organs said to be typically involved in hemorrhagic disease in deer, such as the spleen, skin, and heart." (PMID 36833353, 2023). "Combining the role of TLR3 on innate immunity against EHDV with surveillance of vectors, circulating viruses, and vector habitat characteristics may help predict the severity of outbreaks of epizootic hemorrhagic disease among white-tailed deer." (PMID 36833353, 2023).
hemorrhagic fever (1 paper, 2015). An infectious disease caused by certain viruses or bacteria that can damage the walls of tiny blood vessels, making them leak, and can hamper the blood's ability to clot and cause severe, life-threatening illness. "SNPs significantly associated with eye disease included three different polymorphisms TLR8 and hemorrhagic fever symptoms associated with TLR3, TLR7, TLR8 and MyD88." (PMID 25756647, 2015).
Hepatic steatosis (1 paper, 2015). Steatosis is a term used to denote lipid accumulation within hepatocytes. "Moreover, the absence of TLR-3 protected against the development of hepatic steatosis after 33 weeks of HFD and reduced expression levels of TNFα in liver." (PMID 25867514, 2015).
hyperlipidaemia (1 paper, 2013). "The data from this study suggests that hyperlipidaemia leading to endogenous activation of TRIF signalling is pro-atherogenic, however, TLR3 deficiency seemed protective as TLR3 knockouts exhibited disease enhancement." (PMID 23880853, 2013).
Interstitial pneumonitis (1 paper, 2009). "The pulmonary edema and interstitial pneumonitis were modestly attenuated and the bronchiolar epithelial hypertrophy observed in the wild type mice treated with Poly(I:C) was markedly attenuated in the TLR3 KO mice." (PMID 19486528, 2009).
intestinal tumors (1 paper, 2024). "A tempting untested hypothesis is that the absence of TLR-3 on the outward-facing apical membrane of TSIPs in intestinal tumors could alter the anti-tumoral activity of TLR-3 and enhance tumor immune escape." (PMID 38465512, 2024).
keratitis (1 paper, 2014). A corneal disease that is characterized by inflammation of the cornea. "Stromal infiltration of CD68+ve positive cells was seen in both herpetic and gram-negative keratitis sections, associated with TLR3 and TLR4 expression in the corneal epithelium, respectively." (PMID 24736562, 2014).
kidney damage (1 paper, 2014). "Overall, the absence of TLR-3 is associated with lower cumulative kidney damage and maintained renal blood perfusion within the first 24 hours of reperfusion." (PMID 24736450, 2014).
latent infection (1 paper, 2022). "Our proposal is to enhance trained immunity with dendritic cell adjuvants such as the TLR3 agonist ARNAX to lower the antigen threshold for detecting latent infection and cancer and facilitate the creation of more sensitive and effective preventive vaccines." (PMID 36552770, 2022).
leiomyosarcoma (1 paper, 2023). An uncommon, aggressive malignant smooth muscle neoplasm, usually occurring in post-menopausal women. "Similarly, the survival rate of patients with high TLR3 mRNA levels is significantly higher in leiomyosarcomas and in a cohort of Ewing sarcoma tumors from children, adolescent and young adults (AYA)." (PMID 37414800, 2023).
leukocytosis (1 paper, 2017). "The peripheral inflammatory parameters (C-reactive protein concentration, leukocytosis) and CSF cellular parameters did not correlate with TLR3 SNPs (not shown)." (PMID 28646884, 2017).
liver failure (1 paper, 2013). A liver disease characterized by the liver losing or has lost all of its function. "In fasted wildtype (WT) mice, APAP caused significant cellular necrosis, edema, and inflammation in the liver, and the de novo expression and activation of TLR3 was found to be necessary for APAP-induced liver failure." (PMID 23762449, 2013).
lysosomal storage disease (1 paper, 2023). A metabolic disorder caused by mutations in proteins critical for lysosomal function, including lysosomal enzymes, lysosomal integral membrane proteins, and proteins involved in the post-translational modification and trafficking of lysosomal proteins. "Lysosomal storage disease genes include GRN, GPNMB, GAA, and CHIT1 which, according to STRING analyses, interact with CD68, CD63, and TLR3, and are known to have lysosomal membrane function." (PMID 37422510, 2023).
macular degeneration (1 paper, 2023). Loss of vision in the central portion of the retina (macula), secondary to retinal degeneration. "Vice et versa, the expression of the L412F polymorphism is associated with a reduced risk of macular degeneration, which was shown to result from a decreased propensity of this TLR3 allele to drive retinal cell apoptosis." (PMID 37414800, 2023).
malignant brain tumors (1 paper, 2021). "Eight PRRs were identified as up-regulated after the second immune challenge, including perlucin 4, C1q domain containing protein 2, scavenger receptor class B-like protein, deleted in malignant brain tumors 1 protein-like, TLR, TLR2, TLR3 and TLR8." (PMID 34295333, 2021).
mantle cell lymphoma (1 paper, 2014). Mantle cell lymphoma is a rare form of malignant non-Hodgkin lymphoma affecting B lymphocytes in the lymph nodes in a region called the ``mantle zone''. "In mantle cell lymphoma (MCL), TLR1, TLR4, TLR7, TLR9 and TLR10 exhibit significant mRNA levels, whereas TLR2, TLR3, TLR5 and TLR8 are negative." (PMID 25112836, 2014).
metastatic melanoma (1 paper, 2025). A melanoma that has spread from its primary site to another anatomic site. "The adjuvant CAF09b, composed of dimethyldioctadecylammonium (DDA), the MINCLE agonist monomycoloyl glycerol (MMG) and the TLR3 agonist Poly(I:C), is effective at inducing CD8 T cell responses and is currently tested in neoepitope peptide-based vaccines against metastatic melanoma in humans." (PMID 39983329, 2025).
middle ear inflammation (1 paper, 2005). "The increased expression of TLR2, TLR3 and TLR4 as a consequence of allergen exposure is in line with a previous report demonstrating an increase of TLR2 protein in chronic middle ear inflammation." (PMID 16146574, 2005).
Miscarriage (1 paper, 2024). A pregnancy that ends at a stage in which the fetus is incapable of surviving on its own, defined as the spontaneous loss of a fetus before the 22th week of pregnancy. "Additionally, the impact of herpes simplex viruses 1 and 2 on the expression of TLR2, TLR3, TLR4 and TLR8 in predicting miscarriage onset has been studied." (PMID 39273663, 2024).
myasthenia gravis (1 paper, 2020). Myasthenia gravis (MG) is a rare, clinically heterogeneous, autoimmune disorder of the neuromuscular junction characterized by fatigable weakness of voluntary muscles. "Unlike autoimmune myocarditis, myasthenia gravis (MG) and its models require activation of TLR3 and TLR9, but not TLR2 and no NOD or NLR involvement has been reported for either patients or in animal models (although this may be because no one has yet looked for it)." (PMID 32629865, 2020).
Myocardial fibrosis (1 paper, 2024). "Of the other genes that had significant association with myocardial fibrosis, LIMS1, TLR3 and PLB1 had heart enhanced interactions." (PMID 38848015, 2024).
nephrolithiasis (1 paper, 2021). The presence of a calculus in the pelvis of the kidney; this is most often composed of mineral salts and proteins. "Genes in this crosstalk include those previously reported to be of functional relevance to nephrolithiasis, such as protein kinase C (PRKCA, PRKCB, and PRKCZ), markers (CD40 and TLR3), and autophagy (MTOR and SQSTM1), thus validating our genetic prioritization at the gene and pathway level." (PMID 34489936, 2021).
nephrotic syndrome (1 paper, 2020). A collection of symptoms that include severe edema, proteinuria, and hypoalbuminemia; it is indicative of renal dysfunction. "Immune system derangements resulting in an inflammatory state have been described during proteinuria in nephrotic syndrome and include a few mediators of inflammation, like IL17 A, TNF-α, IFN-γ, TLR-3, and CRP." (PMID 33585371, 2020).
neuropathy (1 paper, 2019). A disorder affecting the nervous system that manifests with pain, tingling, numbness, and/or muscle weakness. "Moreover, TLR3 competitive inhibitor could not ameliorate ZIKV-mediated neuropathy of NPC organoids." (PMID 30952992, 2019).
neurosarcoidosis (1 paper, 2023). A sarcoidosis that involves the nervous system. "The minor alleles at three genetic variants are associated with increased risk of neurosarcoidosis: rs3775291 near TLR3 (p = 0.003; OR = 2.01), rs4921492 near IL12B (p = 0.008; OR = 1.88), while the minor allele at rs12793173 near LOC102723568 (p = 0.006; OR = 0.53) is protective." (PMID 37621457, 2023).
of the CNS (1 paper, 2015). "HSE, a rare and potentially fatal disease of the CNS (central nervous system), is caused by mutations in genes encoding components of the TLR3 signalling network, such as TRIF, TBK1, IRF3 and TLR3 itself." (PMID 25891802, 2015).
ovarian tumors (1 paper, 2018). "PRR polymorphisms have been implicated in poor clinical outcomes in some cancers, an example of which is the overexpression of TLR3 in human ovarian tumors." (PMID 30613350, 2018).
peptic ulcer disease (1 paper, 2024). A digestive system disease characterized by discontinuation in the inner lining of the gastrointestinal (GI) tract because of gastric acid secretion or pepsin. "TLR3 expression decreased with disease progression, from erosion to peptic ulcer disease to GC (p < 0.001)." (PMID 39451226, 2024).
pneumonitis (1 paper, 2021). An inflammatory process affecting the lung parenchyma. "Interestingly, a recent study in human patients revealed that TLR3 deficiency in children underscores IAV-mediated pneumonitis, suggesting a protective role for TLR3 in humans during natural IAV infection." (PMID 34610835, 2021).
polyp (1 paper, 2020). A usually exophytic mass attached to the underlying tissue by a broad base or a thin stalk. "In contrast, TLR3 and TLR5 were downregulated in all patient polyp types compared with normal tissue samples." (PMID 33255933, 2020). "In addition, lower expression rates were observed for TLR3 and TLR5 in all polyp groups in contrast to normal individuals (p-value < 0.001)." (PMID 33255933, 2020).
pouchitis (1 paper, 2024). Acute inflammation in the intestinal mucosa of the continent ileal reservoir (or pouch) in patients who have undergone ileostomy and restorative proctocolectomy (proctocolectomy, restorative). "The expression of Toll-like receptors (TLRs) is also altered, with a decreased expression of TLR3 and increased expression of TLR5 in normal ileal pouch, and an upregulation of TLR2 expression in pouchitis and upregulation of TLR4 in both normal pouch and pouchitis." (PMID 38929596, 2024).
prediabetes (1 paper, 2019). "Out of all the TLRs tested, IL-33 was directly correlated with TLR3 and TLR9 in individuals with T2D and prediabetes, respectively." (PMID 31073344, 2019).
pterygium (1 paper, 2025). A wedge-shaped fibrovascular lesion arising from the bulbar conjunctiva and extending to the cornea. "We previously suggested that pterygium development may be linked to RNA released from abnormally growing PECs: U1 RNA released from ultraviolet B (UVB)-damaged cells may activate TLR3." (PMID 41334960, 2025). "We hypothesized that TLR3 contributes significantly to UV-related pterygium by recognizing self-noncoding RNA danger-associated molecular patterns (DAMPs) released from UV-damaged necrotic cells." (PMID 41334960, 2025). "TLR3, TRIF, and the phospho-NF-κB/NF-κB ratio significantly increased after UVB irradiation, and RNase A treatment decreased their levels in a dose–response manner, indicating that RNA played an important role in the activation of TLR3 signaling in pterygium." (PMID 41334960, 2025). "We previously demonstrated that the levels of expression of TLR3, p63, and NF-κB were higher in pterygium than in ipsilateral pterygium-free conjunctiva." (PMID 41334960, 2025). "Toll-like receptor 3 (TLR3) detects RNA from pterygium epithelial cells (PECs)." (PMID 41334960, 2025). "Several small noncoding RNAs, whose expression was induced by UVB irradiation, may be a possible novel therapeutic target for pterygium treatment through activation of the TLR3 signaling pathway." (PMID 41334960, 2025). "Results showed that RNase A reduced TLR3, TRIF, and phospho-NF-κB in PECs, which confirmed that RNA from UVB-damaged PECs was necessary for activating the TLR3/NF-κB pathway in pterygium." (PMID 41334960, 2025).
pulpitis (1 paper, 2017). Inflammation of the dental pulp. "Furthermore, deciduous pulps with pulpitis suffered higher expressions of proinflammatory cytokines (IL-6 and MCP-1) and innate immune response (TLR1, TLR2, TLR3, TLR6, and TLR8) than pulps without pulpitis." (PMID 28377925, 2017).
relapsing-remitting MS (1 paper, 2019). "We utilized prospectively collected serum from relapsing-remitting MS patients (n = 18) and controls (n = 16) and confirmed lower concentration of TLR3 and higher concentration of mechanistically related TLR4 in MS EVs compared to controls." (PMID 31509962, 2019).
Respiratory tract infection (1 paper, 2020). An infection of the upper or lower respiratory tract. "The data presented above, and the results obtained in our study of the TLR3 gene, may explain the higher incidence of equine herpesvirus-1 (EHV-1) and equine herpesvirus-4 (EHV-4), responsible for massive respiratory tract infections in foals and young horses." (PMID 33114637, 2020).
retinal disease (1 paper, 2019). "Moreover, its upstream regulatory factor (e.g., TLR3) and downstream target (e.g., IFN-β) are involved in retinal disease in old animals." (PMID 31281243, 2019).
rhabdomyosarcoma (1 paper, 2023). A rare aggressive malignant mesenchymal neoplasm arising from skeletal muscle. "Interestingly, this anti-tumoral effect was lost in cells expressing the homozygous TLR3 L412F polymorphism, which is enriched in a rhabdomyosarcomas cohort." (PMID 37414800, 2023).
salpingitis (1 paper, 2018). Acute or chronic inflammation of the fallopian tube. "In mid-stage infection, TLR3-/- mice exhibited significantly enhanced lymphocytic endometritis and salpingitis than wild-type mice." (PMID 29624589, 2018). "Furthermore, TLR3-/- mice exhibited significantly higher lymphocytic endometritis and salpingitis than wild-type mice during mid-stages of genital tract infection." (PMID 29624589, 2018).
schistosomiasis (1 paper, 2024). An infectious disease caused by parasitic trematodes of the genus Schistosoma that colonize human blood vessels and release eggs that can cause granulomatous reactions leading to acute (swimmer's itch or acute schistosomiasis syndrome) or chronic disease. "We demonstrated that TLR3 deficiency led to reduced numbers of peripheral blood WBC and restored the peripheral blood RBC numbers, platelet and HGB content of infected mice, which suppressed the development of schistosomiasis." (PMID 38172683, 2024).
scrapie (1 paper, 2022). A fatal disease of the nervous system in sheep and goats, characterized by pruritus, debility, and locomotor incoordination. "In the thalamus, TLR6, MyD88, and CD36 were significantly upregulated in the scrapie-infected group (p < 0.05), while TLR2 and TLR3 displayed a tendency towards upregulation (p < 0.1)." (PMID 35408945, 2022).
sexually transmitted disease (1 paper, 2016). A Disease due to or propagated by sexual contact. "This works further highlights that TLR3/MDA5 agonists such as Poly(I:C) may be valuable adjuvants for ID vaccination against sexually transmitted diseases." (PMID 29263853, 2016).
squamous intraepithelial lesions (1 paper, 2024). "In our study, the evaluation of TLR3 expression revealed that HPV infection was accompanied by higher expression levels compared to cases with the presence of squamous intraepithelial lesions (SILs) but without viral replication." (PMID 39273663, 2024).